NRXN1 (neurexin 1)
Diseases named in the same sentence as NRXN1 in open-access papers (continued):
Sharing a sentence is not in itself a finding about the gene and the disease.
schizophrenia (continued). "In order to explore the association of NRXN1 polymorphisms with schizophrenia, we made a case-control association study in Chinese Han population." (PMID 21477380, 2011). "In summary, we found that variants within the NRXN1 gene influence brain morphometry with a susceptibility pattern relevant to both schizophrenia and ASD." (PMID 21687627, 2011). "Among the CNVs more typically associated with schizophrenia, those located in the NRXN1 gene and at the 15q11.2, 15q13.3 and 16p13.11 loci collectively were found in 3% of our sample, a figure close to prevalence rates already reported." (PMID 20967226, 2010). "Herein, this review focuses on the most recent and relevant literature concerning the genetic and molecular mechanisms through which NRXN1 variants contribute to the pathogenesis of neuropsychiatric disorders, particularly schizophrenia and autism spectrum disorder." (PMID 42211283, 2026). "Neurexin 1 (Nrxn1) is crucial for synapse formation, transmission, and plasticity, and is implicated in learning, memory, and multiple neuropsychiatric disorders including schizophrenia and autism." (PMID 41522609, 2026). "For example, Nrxn1, a brain-specific gene important in cerebellar and prefrontal cortex neuronal cell survival and implicated in neurological diseases (e.g., schizophrenia, Pitt Hopkins, autism) exhibits multiple intragenic RE1 motifs and transcriptional diversity." (PMID 41278839, 2025). "For example, NRXN1, a cell surface protein involved in cell-cell interactions, exocytosis of secretory granules and regulation of signal transmission, has been associated with autism, schizophrenia and nicotine dependence." (PMID 38570518, 2024). "Additionally, our review underlined the integral role of specific neurexin variants, primarily NRXN1, in the pathology of schizophrenia." (PMID 38380150, 2024). "Neurexin 1 (NRXN1) deletions are linked to increased risk in schizophrenia." (PMID 38075269, 2023). "ASD0060 carried a deletion at 2p16.3 involving exons of a haploinsufficiency gene NRXN1 inherited from his phenotypic normal father, which is associated with susceptibility to autism, schizophrenia (SCZD17), developmental delay, intellectual disability, and dysmorphic features." (PMID 37035742, 2023). "Deletions in the coding region of NRXN1 increase schizophrenia risk, which might be related to NRXN1 expression activity." (PMID 36192459, 2022). "The CNV Analysis Group of the Psychiatric Genomic Consortium (PGC) conducted a large-scale analysis and discovered that recurrent CNVs at eight genetic loci were pathogenic to schizophrenia, including 1q21.1, 2p16.3 (NRXN1), 3q29, 7q11.23, 15q13.3, distal 16p11.2, proximal 16p11.2, and 22q11.2." (PMID 35008879, 2021). "Current CNV studies of TS and OCD are smaller than those conducted for DD, ASD and schizophrenia, although CNVs have also been shown to increase risk for these disorders, with deletions of NRXN1 and duplications of CNTN6 currently implicated in TS and 16p13.11 deletions in OCD." (PMID 33752146, 2021). "In addition, genetic variation within NRXN1 has been shown to confer neural and cognitive susceptibility common to both schizophrenia and ASDs, providing one possible mechanistic explanation for the pleiotropic effects in the brain." (PMID 23840597, 2013). "As ASDs and schizophrenia are thought to be multigenic disorders, our findings suggest that deletions within the NRXN1 gene found in patients may be associated with the impairments seen in social behaviours." (PMID 23840597, 2013). "Since exonic deletions in the NRXN1 gene in human patients were linked to autism and schizophrenia, we wanted to test whether the impairment in transmission may also lead to behavioural abnormalities related to the diseases." (PMID 23840597, 2013). "Genome-wide CNV studies previously implicated NRXN1 deletions in autism and schizophrenia." (PMID 22384383, 2012).
schizophrenia (continued). "And our data of both SNPs and haplotypes showed that the NRXN1 might be a susceptibility gene of schizophrenia in Chinese Han population." (PMID 21477380, 2011). "In the present study, we want to discuss that common SNPs in NRXN1 gene, other than rare CNVs, might also be associated with schizophrenia in Chinese Han population." (PMID 21477380, 2011). "Our case-control association study suggested that NRXN1 gene may play a role in genetic susceptibility to schizophrenia." (PMID 21477380, 2011). "Recent research has implicated that mutations in the neurexin-1 (NRXN1) gene on chromosome 2p16.3 might play a role in schizophrenia, autism, and nicotine dependence." (PMID 21477380, 2011). "Several other published literatures also supported that the rare CNVs in NRXN1 gene may be associated with schizophrenia and other mental disorders." (PMID 21477380, 2011). "Our findings suggest that NRXN1 might represent a major susceptibility gene for schizophrenia in Chinese Han population." (PMID 21477380, 2011). "Three haplotypes at the NRXN1 gene were found to be associated with schizophrenia." (PMID 21477380, 2011). "Therefore, it is apparent that disruptions of the NRXN1 gene, especially deletions, confer risk to a range of neurodevelopmental phenotypes, including ASDs, schizophrenia, and mental retardation." (PMID 21687627, 2011). "Several previous studies have suggested that the NRXN1 gene might be the susceptibility gene of schizophrenia and other neurodevelopmental disorders." (PMID 21477380, 2011). "Taken together, our findings provide evidence that genetic variation in NRXN1, a risk gene for schizophrenia and ASD, may confer neural and cognitive susceptibility common to both disorders." (PMID 21687627, 2011). "Heterozygous copy-number and missense variants in CNTNAP2 and NRXN1 have repeatedly been associated with a wide spectrum of neuropsychiatric disorders such as developmental language and autism spectrum disorders, epilepsy and schizophrenia." (PMID 21827697, 2011). "We found five patients with a CNV occurring in one of the regions most convincingly implicated as risk factors for schizophrenia: NRXN1 and the 16p13.1 regions were found to be deleted in single patients and 15q11.2 in 2 patients, whereas the 15q13.3 region was duplicated in one patient." (PMID 20967226, 2010). "Together with the enrichment in ADHD of neurodevelopmental copy number variations implicated in schizophrenia (e.g., 22q11.2, NRXN1), these observations support a genetic-stratification hypothesis: ADHD–psychotic and ADHD–bipolar lineages may reflect partially distinct allele constellations." (PMID 41327397, 2025). "Thus, the dysfunctions associated with NRXN1 mutations in schizophrenia may also extend to the regulatory roles of NRXN1 circRNAs, further contributing to dysregulation of synapse formation and transmission." (PMID 39966624, 2025). "NRXN1 and its interacting genes are compelling candidates for suicide risk, as they are associated with a broad spectrum of neurological and psychiatric disorders (autism, schizophrenia, anxiety, depression, bipolar disorder, and attention deficit hyperactive disorder)." (PMID 34168285, 2021). "Finally, it is worth mentioning that the previous identification of mutations in the NRXN1 gene affecting α and β isoforms associated with autism, mental retardation and schizophrenia strongly suggests a role for synaptic defects mediated by neurexins in mental diseases." (PMID 21559374, 2011). "However, the manner in which NRXN1 gene variation may be related to brain morphology to confer risk for ASD or schizophrenia is unknown." (PMID 21687627, 2011). "With the identification of rare copy number risk variants implicating specific genes (e.g. VIPR2 and NRXN1) it is increasingly possible to investigate molecular aetiology in patient subgroups to establish whether schizophrenia represents one or many different disease processes." (PMID 22547958, 2011).
schizophrenia (continued). "Given that such deletions confer susceptibility to both schizophrenia and ASD, we hypothesized that NRXN1 polymorphisms would confer an intermediate phenotype related to schizophrenia and ASD, via effects on neural structures and cognitive function altered in both disorders." (PMID 21687627, 2011). "Mutations in the human neurexin 1 (NRXN1) gene are associated with neurodevelopmental disorders including autism and schizophrenia." (PMID 41648563, 2026). "Another GWAS studies have consistently found associations between copy number variation (mainly deletions) in NRXN1 and schizophrenia." (PMID 40259965, 2025). "Genomic alterations in NRXN genes (NRXN1, NRXN2, and NRXN3) are associated with neuropsychiatric disorders, including autism spectrum disorders and schizophrenia." (PMID 39518976, 2024). "In this study, we identified mechanisms by which a conserved autism and schizophrenia relevant gene, NRXN1/nrx-1, influences behavior." (PMID 38036526, 2023). "iPSC-derived NRXN1+/− neurons from individuals with schizophrenia showed a reduction in neuronal activity that ameliorated with overexpression of the wild-type NRXN1α." (PMID 37441676, 2023). "Studies in iPSC-derived neurons from schizophrenia patients with heterozygous NRXN1 deletions have shown specific deficits in neurotransmitter release and in synaptic function similar to those observed in engineered NRXN1-deficient neurons." (PMID 37507766, 2023). "We found that neurexin 1 (NXRN1) expression, a high probability susceptibility gene for schizophrenia was particularly tightly coupled to FEZ1 expression across our samples." (PMID 37746155, 2023). "Of note, changes in cell-cell adhesion have been associated with other genetic risk factors for schizophrenia, such as in DISC1 and NRXN1 mutations." (PMID 36581615, 2022). "Across the different BBB cell types, the largest difference in gene expression was detected for NRXN1, with reduced expression in schizophrenia MSCs cluster as compared to controls." (PMID 36192459, 2022). "Nevertheless, we found a number of genes in this list that have a reported association to schizophrenia or other neuropsychiatric disorders, for example, TENM4, NXN, NRXN1, GALNT5, SHANK3 and RELN." (PMID 36711134, 2022). "The largest difference in gene expression (highest log2FC) was observed for NRXN1, a gene coding for a membrane bounded cellular adhesion molecule, with reduced expression in schizophrenia MSCs cluster as compared to control MSCs." (PMID 36192459, 2022). "Brain morphology can also be influenced by NRXN1 levels, leading to the typical phenotypes of schizophrenia, mental retardation and autism." (PMID 33925709, 2021). "Loss of heterozygosity for NRXN1 and NRXN2 in mice leads to phenotypes associated with autism and schizophrenia." (PMID 34357104, 2021). "There is also evidence that brain expression of NRXN1 is altered in individuals with bipolar disorder or schizophrenia who died by suicide." (PMID 34168285, 2021). "Levels of NRXN1 expression in the prefrontal cortex are changed in schizophrenia and bipolar disorder in comparison to healthy people." (PMID 34357104, 2021). "NRXN1+/− deletions are the most frequent single-gene disruptions associated with ASD, schizophrenia, intellectual disability, ADHD, and epilepsy." (PMID 31893021, 2019). "For example, ASD, intellectual disability (ID), and schizophrenia have been found to share risk loci in FMRP targets, CHD5, CHD8, SCN2A, and neurexin 1 (NRXN1)." (PMID 31481879, 2019). "First, to the best of our knowledge, mutations with large risk to schizophrenia have been reported in at least five genes, DISC1, NRXN1, PRODH, SHANK3, and SLC1A1 according to records in OMIM." (PMID 30745909, 2018). "The deletion encompasses the NRXN1 gene, for which an association with TS, ASD, ID, and schizophrenia has been described." (PMID 29179725, 2017).
schizophrenia (continued). "A recent study found a statistically significant excess of rare missense variants of NRXN1 (MIM 600565) and extremely rare damaging risk variants of AKAP9 (MIM 604001) in schizophrenia patients in Northwest Spain." (PMID 26114114, 2015). "The susceptibility genes (such as DISC1, RELN, GABA, SHANK3, NRXN1, NTNG1, etc.), which were associated with schizophrenia, also confer risk to ASD." (PMID 26204268, 2015). "Neurexins and neuroligins from one of the most studies molecular contributing to synaptic connection have been reported in patients with schizophrenia including neurexin-1, and neuroligin-2." (PMID 26674772, 2015). "Mutations in NRXN1, NRXN2, NLGN2, NLGN4, and SHANK3 genes related to ASD have been also found in schizophrenia patients." (PMID 25780553, 2015). "A family with NRXN1 deletions, schizophrenia and type 1 diabetes has been described, which is plausible because neurexin 1 is expressed in β -cells of pancreas." (PMID 25408897, 2013). "The de novo alterations of the NRXN1 gene and their roles in the pathogenesis of autism and schizophrenia have been reported by some studies." (PMID 21477380, 2011). "Six SNPs in the NRXN1 gene were genotyped in 768 schizophrenia patients and 738 healthy control subjects of Chinese Han population." (PMID 21477380, 2011). "Structural variation in the neurexin-1 (NRXN1) gene increases risk for both autism spectrum disorders (ASD) and schizophrenia." (PMID 21687627, 2011). "We focused on the association of six SNPs spanning a 117.6 kb region locating in an intron near the NRXN1 5'UTR with schizophrenia." (PMID 21477380, 2011). "Further association analysis of haplotypes consist of six SNPs at the NRXN1 gene with schizophrenia were performed." (PMID 21477380, 2011). "In relation to the CNVs most convincingly implicated in the risk for schizophrenia, we found a patient with a deletion of 328 kb erasing the 5′UTR and the first 3 exons of the NRXN1 gene (NM_004801.4) and two patients with a deletion in the 15q11.2 region." (PMID 20967226, 2010). "Prior reports of abnormalities in NRXN1 have focused on populations with specific diagnoses (e.g., autism, schizophrenia)." (PMID 20468056, 2010). "Research has implicated mutations in the gene for neurexin-1 (NRXN1) in a variety of conditions including autism, schizophrenia, and nicotine dependence." (PMID 20468056, 2010). "In our cohort we had three large deletions that encompassed the 3′ end of NRXN1 (200 kb in US, 260 kb and 420 kb in Munich), providing further evidence for this region in schizophrenia pathology." (PMID 19197363, 2009). "Moreover, both schizophrenia and autism spectrum disorder involve deletions and alternative splicing of NRXN1, offering molecular evidence for their comorbidity." (PMID 42211283, 2026). "Here, the most significant RCV association was observed for PTVs in NRXN1, which is associated with non-recurrent single-gene deletions in schizophrenia." (PMID 40753099, 2025). "There is also evidence that genetic variants common to schizophrenia and autism spectrum disorder, such as mutations in the SHANK3, NRXN1, and CNTNAP2 genes, may contribute to the occurrence of autistic phenotypes in some patients with schizophrenia." (PMID 40724876, 2025). "However, while wild-type isoforms are generally conserved, mutant isoforms can be more diverse with over 30 isoforms identified in NRXN1+/− cases with schizophrenia." (PMID 37441676, 2023). "Importantly, a genome-wide association analysis searching for loci associated with CoQ10 serum levels identified COLEC12 and NRXN-1, which have also been associated with neuropsychiatric disorders, including Alzheimer's Disease, ASD and Schizophrenia." (PMID 35308885, 2022).
schizophrenia (continued). "Whereas most CNVs associated with schizophrenia encompass multiple genes, the deletion of chromosome 2p16.3 specifically affects the NRXN1 gene encoding the synaptic cell adhesion molecule, neurexin-1, which is involved in the regulation of synaptic development and in synaptic transmission." (PMID 34502372, 2021). "In conclusion, depending on the collected data, it was revealed that rs13381800 SNP in TCF4 gene and rs17039988 SNP in NRXN1 gene were not risk factors for schizophrenia in this sample of Iranian patients with schizophrenia." (PMID 32071599, 2019). "In the present study, it was hypothesized that there is a correlation between rs13381800 in the promoter region of the TCF4 gene and rs17039988 in the promoter region of the NRXN1 gene and schizophrenia." (PMID 32071599, 2019). "However, in three regions (16p13.1, 1q21.1, and NRXN1) CNVs were more prominent among individuals with schizophrenia." (PMID 28855529, 2017). "NRXN1 is related to autism, Asperger, schizophrenia, and pervasive developmental disorder." (PMID 26742492, 2016). "Neurexin1 (NRXN1) is among the genes associated with both ASD and schizophrenia." (PMID 25968177, 2015). "Due to the link between NRXN1, ASDs and schizophrenia in humans, these results are compelling." (PMID 23840597, 2013). "Based on these findings, we hypothesized that the NRXN1 might be a strong candidate gene for schizophrenia." (PMID 21477380, 2011). "Although no connection has been found between NRXN1 and AD yet, this gene has been implicated in autism, schizophrenia, nicotine and alcoholism dependence, and mental retardation." (PMID 20405009, 2010). "In addition, recent studies have reported common genes that are involved in both ASD and schizophrenia, for example, association of gene DISC1 (disrupted in schizophrenia 1) and copy number variations in gene NRXN1 (neurexin 1)." (PMID 18632090, 2008). "The higher methylation reported for MAPT and NRXN1 after THC consumption was also interpreted as possibly disadvantageous in schizophrenia, as higher methylation generally leads to reduced readability of genes, which might further impair reduced synaptic connections." (PMID 35859599, 2022). "Deletion of the neurexin-1 gene alters synapse function and neuronal connectivity in astrocytes, leading to inhibition of differentiation, supporting the established role of neurexin-1 in neurodevelopmental diseases such as schizophrenia, Tourette syndrome, epilepsy and autistic spectrum disorder." (PMID 34403115, 2021). "NRXN1 was reportedly associated with neurological diseases, such as tardive dyskinesia and schizophrenia; however, there were no reports about NRXN1 in the field of coronary heart disease; besides, it was reported that NRXN1 was associated with high nicotine addiction." (PMID 33224271, 2020). "Therefore, in the present study, TCF4 and NRXN1 genes were selected and a correlation study of rs13381800 in the promoter region of TCF4 gene with rs17039988 in the promoter region of NRXN1 gene was performed in samples collected from individuals with schizophrenia and healthy controls." (PMID 32071599, 2019). "Though the CAMs pathway was associated with schizophrenia in pathway level in both Chinese Han and European population, the significant associated CAMs genes in our dataset were different from those significant CAMs genes (HLA-DQA1, CDH4, NRXN1 and CNTNAP2) reported in European population." (PMID 26674772, 2015). "Some of the mutations of the genes related to ASD, including NRXN1, NRXN2, NLGN2, NLGN4, SHANK3, and SynGAP, have been also found in the schizophrenia patients; for instance, two de novo mutations (R1117X and R536W) were identified in the SHANK3 gene of two families of schizophrenia." (PMID 25780553, 2015). "However, there has been no further evidence of association between NRXN1 polymorphisms and schizophrenia in Chinese Han population." (PMID 21477380, 2011).